EZH2 (enhancer of zeste 2 polycomb repressive complex 2 subunit)
Diseases named in the same sentence as EZH2 in open-access papers (continued):
Sharing a sentence is not in itself a finding about the gene and the disease.
breast cancer (continued). "The protein expression levels of EZH2 and NSD2 were correlated in breast cancer (BC) tissues." (PMID 33665162, 2020). "The expression of EZH2 and SUZ12 was increased in several types of cancers such as prostate, ovarian, and breast cancers, and it initiated tumorigenesis and activated anti-drug responses through preventing the expression of differentiation-related genes and promoting stem cell-like phenotypes." (PMID 33014839, 2020). "The highest EZH2 protein expression levels were observed in TNBC, while the lowest expression levels were found in estrogen receptor (ER)/progesterone receptor (PR)-positive breast cancers with low proliferative index." (PMID 33050946, 2020). "Collectively, these findings suggest that EZH2 directly represses PPP2R2B expression through chromatin modification, and small molecule inhibition of EZH2 restored PPP2R2B expression and abolished the residual p70S6K and 4EBP1 activity in breast cancer." (PMID 33208750, 2020). "Thus, our data indicated that the EZH2-miR-29b/miR-30d-LOXL4 signaling axis regulated macrophage activation and collagen remodeling in breast cancer." (PMID 32754259, 2020). "Other EZH2 inhibitor, GSK343 and GSK236, were also reported to inhibit tumor progression in various cancer, such as glioblastoma, head and neck cancer, and breast cancer." (PMID 32206036, 2020). "Clinical trials for combination of EZH2 inhibition with immunotherapy have also been initiated in urothelial carcinoma, but for breast cancer have not yet been initiated." (PMID 34968306, 2020). "We explored the regulatory mechanism of EZH2, miR-29b/miR-30d, and LOXL4 in breast cancer cells by qRT-PCR, Western blotting, cell proliferation, colony formation, and wound healing assays, xenograft experiments, dual-luciferase reporter assay, and chromatin immunoprecipitation." (PMID 32754259, 2020). "Unlike other EZH2 inhibitors, which are limited to certain hematological malignancies, DZNep has a wide range of therapeutic effects in various tumors, such as breast cancer 6, non-small cell lung cancer 44, and pancreatic cancer." (PMID 31367244, 2019). "Treatment of ErbB2-driven breast cancer cells with the biguanide phenformin, which directly inhibits OXPHOS regardless of the presence of c-Src, activated AMPK and inhibited mTORC1, markedly reducing Ezh2 and Suz12 protein expression." (PMID 31263101, 2019). "A weak negative correlation was observed between EZH2 and its targets in breast cancer cell lines MERAV dataset (except for POMT2 and VGLL4 where a positive correlation was detected)." (PMID 30760814, 2019). "Furthermore, correlation analysis in TCGA glioblastoma and breast cancer datasets showed a positive correlation with the expression of HOTAIR and EZH2." (PMID 31367244, 2019). "An enhanced expression of EZH2 was observed in nicotine treated breast cancer cells, xenografts and breast cancer patients with smoking history in comparison to non-smoking samples." (PMID 30760814, 2019). "In accordance with our results, AGAP2-AS1 was validated to exert oncogenic functions partly by suppressing the transcription of downstream targets by interacting with epigenetic proteins, such as EZH2, LSD1, and CBP (CREB-binding protein), in NSCLC, gastric cancer and breast cancer." (PMID 31186379, 2019). "In breast cancer, where ANCR remains transcriptionally dormant, hyperactivity of EZH2 leads to an increase of the repressive H3K27me3 mark in promoter regions of EZH2 target genes (such as tumor-suppressors E-cadherin, HOXA10, etc.)which normally repress EMT progression." (PMID 31658672, 2019). "As expected, partial NKILA silencing exerted a negative effect in both breast cancer cell lines by augmenting nuclear NF‐κB levels, EZH2 expression and H3K27 methylation." (PMID 31282094, 2019). "The inhibition role of LINC01133 on breast cancer invasion and metastasis may partly through restraining SOX4 transcription by binding with EZH2." (PMID 31557401, 2019).
breast cancer (continued). "However, the role of EZH2 in this setting is unclear due to the context-dependent functions of PRC2 and the heterogeneity of breast cancer." (PMID 31263101, 2019). "ANCR-mediated EZH2 degradation may play a key role in weakening the ability of initiating EMT and metastasis programs in breast cancer cells." (PMID 31214490, 2019). "However, significantly reduced clonogenic growth was observed at the concentration of 40μM AQB in glioblastoma and breast cancer cell lines as well as cervical cancer, gastric cancer and melanoma cells which expressed elevated levels of HOTAIR and EZH2." (PMID 31367244, 2019). "Upon EZH2 knockdown, fold change in the target gene expression for GPNMB, CoL5A1, POMT2, PMEPA1, VGLL4 and SUMF1 was found to be 1.3, 2.8, 2.2, 2, 1.7 and 1.8, respectively in MCF-7 breast carcinoma cells as detected by qPCR." (PMID 30760814, 2019). "The results suggested that EZH2 and SMYD3 were in high expression in breast cancer tissues." (PMID 29089464, 2018). "In breast cancer, however, we observe that T367 phosphorylation appears to favor an H3K27me3-independent oncogenic mechanism without significantly affecting EZH2 protein stability." (PMID 30022044, 2018). "The results suggested that EZH2 and SMYD3 were in high expression in breast cancer cells." (PMID 29089464, 2018). "In the MDA-MB-231 cell line, an ER (estrogen receptor)-negative cell line, EZH2 positively activated the transcription of NF-κB target genes in a methyltransferase-independent way, which contributed to aggressiveness of these breast cancer cells." (PMID 34991274, 2018). "Besides, our results revealed that EZH2 and SMYD3 were in high expression in breast cancer tissues and cells." (PMID 29089464, 2018). "PNAs-based strategy blocks the ability of lncRNA HOTAIR to interact with EZH2, subsequently reduces HOTAIR-EZH2 activity and inhibits ovarian and breast cancer cell invasion, which may be suitable for other solid cancers, such as glioma." (PMID 29458374, 2018). "Samples from smoking and never-smoked breast cancer patients, cell lines and xenografts were assessed for EZH2 expression level and its functional role in response to NIC in breast cancer pathogenesis." (PMID 29396474, 2018). "Like EZH2, we found that FOXC1 functions in a context-specific manner in breast cancer." (PMID 29959321, 2018). "Similarly, in the breast cancer cell lines, MCF-7 and T47D, co-IP and GST-pulldown experiments revealed that EZH2 was found to interact with ERα and β-CATENIN and to induce the transcription of their target genes." (PMID 34991274, 2018). "As mediating the activation of EMT and invasion, EZH2 could increase metastasis in many cancers, such as CRC, melanoma, and breast cancer." (PMID 29556394, 2018). "We also utilized PDX models, arguably the most relevant existing human preclinical models, to illustrate the significant effect of EZH2 methyltransferase inhibition on spontaneous metastasis in Luminal B but not HER2+ breast cancer." (PMID 29959321, 2018). "Taken together, our data highlighted that CUL1 regulated EZH2 expression to promote the production of autocrine expression of the autocrine cytokines CXCL8 and IL11, and finally significantly aggravating the breast cancer cell metastasis through the PI3K–AKT–mTOR signaling pathway." (PMID 30578411, 2018). "However, in Tamoxifen-resistant breast cancer tissues, the GREB1 promoter becomes more methylated via the action of the histone lysine N-methyltransferase EZH2, leading to the epigenetic downregulation of GREB1." (PMID 30154312, 2018). "A phospho-deficient EZH2 mutant promoted proliferation to similar levels of wild type EZH2 but failed to promote breast cancer cell migration, invasion, and adhesion." (PMID 30022044, 2018). "In this study, we show that phosphorylation of EZH2 at T367 specifically regulates the adhesive, migratory, and invasive properties of breast cancer cells without affecting their proliferation abilities." (PMID 30022044, 2018).
breast cancer (continued). "Result of Cox multivariate analysis showed that EZH2 rs12670401, EZH2 rs6464926 and clinical staging, mRNA and protein expression of EZH2 and SMYD3, lymph node metastasis, HER2 status, and metastasis situation were independent prognostic factors for survival rate of breast cancer patients." (PMID 29089464, 2018). "To test the relevance of cytoplasmic EZH2 to the neoplastic functions of breast cancer we developed an EZH2 mutant lacking the nuclear localization domain (ΔNLS-EZH2)." (PMID 30022044, 2018). "Samples from smoking breast cancer patients showed distinguished enhanced EZH2 expression in comparison to non-smoking ones." (PMID 29396474, 2018). "In order to understand the potential molecular mechanism of Zfp217 in adipogenesis, we surveyed the reports concerning Zfp217 or adipogenesis in the past decades, and found that Zfp217 was bound to Ezh2 and participated in histone modification in MCF7, which is a breast cancer cell line." (PMID 28653987, 2017). "HOTAIR also silences miR-568 via recruitment of both EZH2 and LSD1 to the miR-568 promoter in breast cancer cells, leading to derepression of the miR-568 target NFAT5, which induces of EMT and invasion in breast cancer via transcriptional activation of calcium binding protein S100A4." (PMID 28430163, 2017). "Furthermore, recent studies have reported that the expression of EZH2, a catalytic subunit of PRC2, is up-regulated in several advanced cancers, such as lung cancer, breast cancer, and prostate cancer." (PMID 28423699, 2017). "Our previous study has demonstrated that ANCR interacts with EZH2 and promotes the CDK1-EZH2 binding to increase its phosphorylation at Thr-345 and Thr-487 residues, resulting in EZH2 ubiquitination and degradation in breast cancer cells." (PMID 28978036, 2017). "Of note, EZH2 physically interacts with and supports the constitutive activation of NF-κB target gene expression in estrogen receptor (ER)-negative breast cancer cells independently of its histone methyltransferase activity." (PMID 28758948, 2017). "In the present study, we showed that pharmacological inhibition of EZH2 using a novel EZH2 inhibitor ZLD1039, reduced cell proliferation, induced breast cancer cell apoptosis, and led to the regression of three established breast tumor xenografts in mice with excellent tolerance." (PMID 26868841, 2016). "Collectively, these data confirm the dependency of breast cancers on PRC2 activity and provide evidence that the pharmacological inhibition of EZH2 could provide a basis for its use as a therapeutic intervention in breast cancers." (PMID 26868841, 2016). "ZLD1039-treated breast cancer cells exhibited decreased H3K27me3 and H3K27me2 without changes in EZH2 and other H3 methylation markers." (PMID 26868841, 2016). "ZLD1039 considerably inhibited EZH2 methyltransferase activity with nanomolar potency, decreased global histone-3 lysine-27 (H3K27) methylation, and reactivated silenced tumor suppressors connected to increased survival of patients with breast cancer." (PMID 26868841, 2016). "Taken together, these results indicate that inhibition of EZH2 by ZLD1039 may considerable block cell cycle progression and induce apoptosis in breast cancer cells." (PMID 26868841, 2016). "In the present study, we found that EZH2 was significantly downregulated by curcumin; however, we were not able to mimic the conditions of breast cancer to reveal the mechanism by which curcumin inhibits EZH2." (PMID 27049834, 2016). "On the other hand, in ERα-negative basal-like breast cancer cells, EZH2 can form complexes with RelA and RelB, activating the NF-κB pathway." (PMID 26580594, 2015).
breast cancer (continued). "Moreover, it has been shown that EZH2 interacts with the HOTAIR lncRNA and facilitates PRC2 targeting in the genome of breast cancer and promotes breast cancer metastasis." (PMID 26516927, 2015). "Interestingly, recent studies have demonstrated that basal-like breast cancer pathogenesis can be inhibited by the repressive activity of Gata-3 on FOXC1 expression and by the silencing activity of EZH2." (PMID 25962646, 2015). "EZH2 is the catalytic subunit of PRC2 and often over-expressed in breast cancer." (PMID 26378045, 2015). "We used breast cancer samples of different histological subtypes, as well as DLBCL samples, as a guide to determine primary antibody concentrations and incubation times in order to observe gradients of EZH2 and H3K27 methylation IHC expression." (PMID 25762637, 2015). "One report revealed that increased expression of the histone methyltransferase enhancer of Zeste Homolog 2 (EZH2) is induced by BPA with consequent increase in the overall level of histone H3 trimethylation at lysine 27 (H3K27me3), both in human breast cancer cells and in mouse mammary glands." (PMID 25207595, 2014). "In breast cancer cells, GATA3 and EZH2 are functionally antagonistic, suggesting that similar interplay between these two factors may also exist in myeloma." (PMID 25188243, 2014). "A recent report found that extended use of aromatase inhibitors resulted in the recruitment of EZH2 and hence increased H3K27me3 of the homeobox gene HOXC10 in breast cancer cells, ultimately leading to HOXC10 methylation and silencing and resistance to aromatase inhibitors." (PMID 25949794, 2014). "In addition, others have demonstrated that the polycomb repressor complex 2 (PRC2), including binding of SUZ12 and EZH2 to the PGR promoter, contributes to PGR transcriptional repression in breast cancer cells." (PMID 25229191, 2014). "New FC-IBC-02 cell line is the first to be used in studying the functional role of EZH2, although the negative effects of silencing of EZH2 on cell growth have been shown in some breast cancer cell lines including SUM149 cells." (PMID 24294976, 2013). "In this study, using in situ hybridization to evaluate HOTAIR lncRNA expression and immunohistochemistry to evaluate protein expression of EZH2, we confirm that EZH2 and HOTAIR are coexpressed in breast cancer, as they have the same expression score 75.7% of the time (p<0.0001)." (PMID 23133536, 2012). "For EZH2, 4 metastases were negative, 59 were weakly positive, and 38 were strongly positive; in reference, on the primary breast carcinoma array, 24 carcinomas were negative, 159 were weakly positive, and 35 were strongly positive." (PMID 23133536, 2012). "In addition to their role on global chromatin modifications and their ability to reactivate Polycomb-silenced genes, DZNep and LBH589 have also been reported to deplete EZH2 protein from AML and breast cancer cells." (PMID 20634887, 2010). "EZH2 is one of a set of 70 genes whose expression predicts a poor outcome in breast cancer, so it is not surprising that most patients with high EZH2 exhibit this poor prognosis signature." (PMID 19099573, 2008). "Interestingly, DEK and EZH2 mRNA levels tended to be higher in estrogen receptor (ER) negative breast cancers (orange dots)." (PMID 40562540, 2025). "In aggressive forms of breast cancer, EZH2 acts as a differential molecule by serving as a transcriptional repressor of nuclear factor kappa B (NF-κB) target genes in estrogen receptor (ER)-negative and ER-positive breast cancer cell lines." (PMID 39768352, 2024). "Interestingly, the non-canonical function of EZH2 in breast cancer is not the same across different subtypes." (PMID 37664059, 2023). "Therefore, we examined the non-traditional biological function of phosphorylated EZH2 in breast cancer." (PMID 37803297, 2023).
breast cancer (continued). "NOC2L was found to be recruited by Enhancer of zeste homolog 2 (EZH2) and cooperate with EZH2 through physical interaction to promote the methylation of H3K27 in the vicinity of forkhead box O3 (FOXO3) promoter region, leading to the downregulation of tumor suppressor FOXO3 in breast cancer cells." (PMID 36650543, 2023). "Interactions of EZH2 with protein degradation machinery are not unique to breast cancer." (PMID 37664059, 2023). "Additionally, in ER+ breast cancer cells, EZH2 has been found to noncanonically interact with estrogen receptor α (ERα) and β-catenin, forming a ternary complex that binds to MYC promoter at the LEF/TCF-binding sites, thereby inducing its transcription." (PMID 37175580, 2023). "Moreover, EZH2 is able to directly interact with β-catenin and ERα in a PRC2-independent manner to activate cyclin D1 and c-Myc expression upon estrogen stimulation to induce the proliferation of breast cancer cells." (PMID 36076977, 2022). "Moreover, EZH2 overexpression in breast cancer does not always correlate with increased expression of global H3K27me39,39,40." (PMID 36446780, 2022). "Collectively, our data underscore the importance of EZH2-mediated SMAD3 K53/K333 methylation in metastasis and indicate that SMAD3 methylation might function as an important factor in predicting overall survival of patients with breast cancer." (PMID 35085106, 2022). "Moreover, in breast cancer cells, ω-3 polyunsaturated fatty acids such as DHA and EPA induce the degradation of EZH2 by the proteasome pathway, thereby downregulating EZH2 protein levels and alleviating the transcriptional repression of EZH2 target genes such as E-cadherin and IGFBP3." (PMID 36263120, 2022). "However, the role of EZH2 in breast cancer development by affecting macrophage polarization has not been uniformly determined." (PMID 36038549, 2022). "The canonical role of EZH2 has been vastly investigated, but the non-canonical function of EZH2 in breast cancer remains unclear." (PMID 34335938, 2021). "However, that is a distinct phenomenon in breast cancer, as p38 inhibition neither reduced cytoplasmic EZH2 nor increased DLC1 protein in lung cancer cells." (PMID 34862367, 2021). "Overall, based on the experimental data presented above, both YPB and OPB peptides could disrupt YY1-EZH2 interaction, decrease EZH2 recruitment by YY1 to the promoters of target genes, such as PTENP1, and reduce breast cancer cell proliferation and xenograft tumor formation." (PMID 34065631, 2021). "The expression level of the enhancer of zeste homolog 2 (EZH2), deleted in liver cancer 1 (DLC1), is negatively correlated in breast cancer, where the upregulation of EZH2 and the downregulation of DLC1 have been reported in breast cancer tissue and MDA-MB-231 cells." (PMID 34298639, 2021). "Furthermore, we sorted the basal breast cancer patients from low to high according to their mRNAsi values and found that patients with high mRNAsi are usually accompanied by high expression of tumor stem-related genes such as KDM5B, BMI1, MYC, and EZH2." (PMID 34646403, 2021). "Currently, the functions of LOXL4 regulated by EZH2 in breast cancer are not understood." (PMID 32754259, 2020). "Genetic depletion or inhibition of EZH2 by a clinically-available EZH2 inhibitor restores PPP2R2B expression, abolishes the residual phosphorylation of p70S6K and 4EBP1, and resensitizes HER2+ breast cancer cells to anti-HER2 treatments both in vitro and in vivo." (PMID 33208750, 2020). "Similarly, the regulation of UCA1 in As‐induced decreased expression of EZH2 was testified in multiple cell lines, including human prostate cancer cell line PC3, human breast cancer cell line 231, human lung adenocarcinoma cell line A549, and normal human kidney cell line HK2." (PMID 32537408, 2020). "Breast cancer gene 1 (BRCA1) is able to inhibit the binding of EZH2 to HOTAIR and its transfer on the promoter of PRC2 target gene HOXA9 in human BC cells and fibroblasts." (PMID 32397382, 2020).